CRP (C-reactive protein)
Diseases named in the same sentence as CRP in open-access papers (continued):
Sharing a sentence is not in itself a finding about the gene and the disease.
leukocytosis (continued). "Blood investigations showed leukocytosis with a left shift, elevated erythrocyte sedimentation rate (ESR), C-reactive protein (CRP), and ferritin." (PMID 38910713, 2024). "They all had laboratory tests of the severe systemic inflammatory response (leukocytosis, thrombocytosis, high ESR, and high CRP) concerning infection." (PMID 37502695, 2023). "Lab data indicated leukocytosis (WBC: 13,690/μL) with neutrophil predominance and an elevated CRP level of 6.19 mg/dL." (PMID 37176534, 2023). "IL‐10 showed negative correlations with the rest inflammatory markers on the 3rd day (WBC, CRP, ESR, ANC, NLR, and IL‐6), suggesting attenuating effect on IL‐6 levels, but also possible effect on leukocytosis reduction (by decreasing WBC, ANC, and NLR)." (PMID 35762501, 2023). "When exploring this, cell numbers (platelets, white blood cells), neutrophil counts, S100 proteins, CRP, ESR, ferritin, leukocytosis with neutrophilia, serum amyloid, and IL-18 should be considered." (PMID 37771977, 2023). "All of the cases presented had leukocytosis and raised inflammatory markers, i.e., ESR and CRP which indicate significant infection at presentation." (PMID 37905257, 2023). "Therefore, compared to these inflammatory markers, the time to blood culture positivity found in our study (AUC ROC of 0.74, sensitivity of 85% and specificity of 63%) could be a better predictor of true bacteremia than C-reactive protein and leukocytosis, and similar to procalcitonin." (PMID 38597473, 2023). "In the laboratory investigation, the most common features are elevated erythrocyte sedimentation rate (ESR), C-reactive protein (CRP) level, and leukocytosis." (PMID 37980513, 2023). "Laboratory analysis shows hypochromic anemia, leukocytosis, thrombocytosis, increased ESR, and increased levels of CRP." (PMID 36876221, 2023). "On admission, routine blood examination showed leukocytosis (white blood cell (WBC), 11.96 × 109/L), elevated C-reactive protein (CRP, 120 mg/ml), and increased erythrocyte sedimentation rate (ESR, 140 mm/h)." (PMID 37516858, 2023). "When the dose of prednisone was reduced to 10 mg once a day, he presented with a disease flare characterized by fever, generalized rash, arthritis, and abnormal laboratory findings (leukocytosis, elevated ESR and CRP levels)." (PMID 37152309, 2023). "In-hospital laboratory evaluation showed leukocytosis and elevated inflammatory markers (WBC 12.47 × 109/L, NEU 9.80 × 109/L, CRP 202.43 mg/L; procalcitonin 16.81 μg/L; ESR 74 mm/hr)." (PMID 38050281, 2023). "Laboratory evaluations during flares show increased inflammatory markers, such as CRP and ESR, as well as leukocytosis with neutrophilia." (PMID 36876221, 2023). "Laboratory studies typically reveal leukocytosis with elevated erythrocyte sedimentation rate (ESR) and C-reactive protein (CRP)." (PMID 38090635, 2023). "Lab data revealed leukocytosis (WBC: 13,170/μL) with neutrophil predominance, an elevated C-reactive protein (CRP) level of 5.09 mg/dL, and a normal hemoglobin (Hb) level (Hb: 14.9 g/dL)." (PMID 37176534, 2023). "In the pathomorphological assessment, 75% of the subjects who had simultaneously elevated ESR (>4.73) and leukocytosis (>6.96) and reduced ASO (<161.03) and CRP (<0.31) belonged to the tonsillitis group." (PMID 37445557, 2023). "Monogenic ABDs typically have evidence of systemic inflammation with elevated c-reactive protein (CRP) and erythrocyte sedimentary rate (ESR) and/or leukocytosis." (PMID 37342528, 2023). "The laboratory findings observed included the presence of stinging at the bite sites, hemodynamic changes, respiratory disorders, elevated levels of CK, C-reactive protein (CRP), fibrinogen, alanine transaminase (ALT), and leukocytosis." (PMID 36977071, 2023). "She had a leukocytosis of 11.5 with an absolute neutrophilia of 9.03 and a mild absolute monocytosis of 1.0, alkaline phosphatase of 151, ESR of 54, and CRP of 158.4." (PMID 38090635, 2023).
leukocytosis (continued). "He had microcytic hypochromic anemia, leukocytosis with neutrophilia, thrombocytosis, elevated acute phase reactants (erythrocyte ESR and CRP), as well elevated serum levels of ferritin, liver, and muscle enzymes and hypertriglyceridemia." (PMID 37600812, 2023). "Leukocytosis, with dominancy of neutrophils, anemia, thrombocytosis and increased ESR and CRP were the most noticeable laboratory findings." (PMID 36714641, 2022). "Correlation analysis demonstrated that among the 135 synovial lipids that were considered sensitive to both RA itself and leukocytosis, 67 correlated well with the blood ESR, CRP levels, and synovitis score (correlation coefficient (|r|) >0.3)." (PMID 35169224, 2022). "Laboratory results showed leukocytosis with lymphopenia, significantly elevated ESR and C-reactive protein, elevated ferritin, D-dimers, mild elevation of alanine aminotransferase, and γ-glutamyltransferase." (PMID 35628892, 2022). "Serum C-reactive protein was elevated in 116 patients with a median of 57 mg/L (IQR 20–113), and leukocytosis was present in 75 patients (median of 11.5 × 109/L, IQR 8.4–14.5)." (PMID 35735755, 2022). "With regard to laboratory findings, leukocytosis with an elevated percentage of neutrophils, hyperferritinemia, and increased ESR, CRP, procalcitonin (PCT), and lactic dehydrogenase (LDH) are commonly observed in AOSD; elevated liver enzymes are also reported." (PMID 36072947, 2022). "“We were used to prescribe antibiotics based on criteria regarding inflammation: CRP, ESR, and sometimes procalcitonin, and often leukocytosis, neutrophilia, and of course fever and chills." (PMID 35683579, 2022). "Leukocytosis (WBC ≥ 12,000/mm3), high CRP values (≥50 mg/L), and performing abdominal imaging studies at admission were independent factors associated with early antibiotic therapy." (PMID 36670591, 2022). "Laboratory indices often find an elevated C-reactive protein (CRP), erythrocyte sedimentation rate (ESR), and leukocytosis with neutrophilia, which are similar to findings in infectious diseases." (PMID 36072947, 2022). "Initial laboratory results showed leukocytosis (WBC 20 K/microliter), significant thrombocytosis elevated inflammatory markers (CRP 9 mg/dL, ESR 85 mm/h), and mild hypoalbuminemia (albumin 3 g/dl); all muscle enzymes were within normal range." (PMID 35012585, 2022). "In the initial analyses, in which patients were compared with healthy controls, we observed leukocytosis, lymphopenia, thrombocytosis, elevated SII and NLR, hyponatremia, hypochloremia and elevated levels of AST, ALT, LDH and CRP." (PMID 35976368, 2022). "After 2 months of treatment with etanercept, leukocytosis and thrombocytosis were resolved, and erythrocyte sedimentation rate (ESR), C-reactive protein (CRP), serum ferritin, and liver enzymes gradually returned to normal values." (PMID 36064566, 2022). "All had elevated laboratory inflammatory markers, such as C-reactive protein (CRP) and serum amyloid A (SAA), and in some laboratory examinations mild blood leukocytosis, neutrophilia, and increased erythrocyte sedimentation rate were also noted." (PMID 35720340, 2022). "In the multiple logistic regression analysis, leukocytosis (WBC ≥ 12,000/mm3), high CRP values (≥50 mg/L), and performing abdominal imaging studies at admission were independent factors associated with early antibiotic therapy." (PMID 36670591, 2022). "Non-survivors also showed signs of marked inflammation, manifesting as leukocytosis, neutrophilia, and elevated LDH or CRP." (PMID 35854825, 2022). "The analysis in the postoperative period also included triggers of pain such as inflammatory parameters in the two groups: leukocytosis (WBC) levels and CRP values on postoperative day 0, 1, 2, 3 in blood and fluid collected from surgical wound drains." (PMID 35149701, 2022).
leukocytosis (continued). "In the acute stage of KD, leukocytosis with a predominance of neutrophils, anemia, and elevation of acute-phase reactants, such as ESR and CRP, can all occur." (PMID 36467487, 2022). "Laboratory data usually show leukocytosis, increased ESR, and increased levels of C-reactive protein (CRP) and immunoglobulins." (PMID 35346317, 2022). "In our study, leukocytosis (WBC ≥ 12,000/mm3), high CRP values (≥50 mg/L), and performing abdominal imaging studies were independent factors associated with the use of antibiotics in the early days of hospitalization." (PMID 36670591, 2022). "Previous studies have shown that acute short-term exercise can trigger a pro-inflammatory effect presented by elevated secretion of IL-6 and CRP, and to a lesser extent, TNF-α levels, in addition to triggering leukocytosis and oxidative stress." (PMID 36504710, 2022). "All patients were febrile with an elevated level of C-reactive protein (CRP), procalcitonin (PCT), leukocytosis in eight patients, and leucopenia in the last one after the chemotherapy administration." (PMID 35795064, 2022). "Initial laboratory results revealed a high level of inflammatory markers, including a C-reactive protein (CRP) of 156.8 mg/l, an erythrocyte sedimentation rate (ESR) of 100 mm/hour, procalcitonin (PCT) of 13.84, leukocytosis with neutrophilia, and lymphopenia." (PMID 36192799, 2022). "Initial laboratory work showed a new leukocytosis with a WBC count of 28 K/μL, increased C-reactive protein (CRP) of 16.6 mg/dL, and increased erythrocyte sedimentation rate (ESR) of 37 mm/hr." (PMID 35174039, 2022). "Laboratory tests showed leukocytosis (median 16.5 × 109/L; IQR 13.1–18.8) and increased C-reactive protein (median 50.5 mg/L; IQR 31–74.5)." (PMID 34698296, 2021). "Laboratory tests showed marked leukocytosis (mean WBC count 30,239/μL, range 14,080–79,600/μL) and elevated serum CRP levels (mean 11.91 mg/dL, range 0.99–27.43 mg/dL) in all patients described." (PMID 34021462, 2021). "Laboratory tests performed at admission showed leukocytosis [white blood cell (WBC) count, 15,200/μL; neutrophils, 87%] and an elevated serum level of C-reactive protein (CRP, 7.5 mg/dL)." (PMID 34021462, 2021). "At diagnosis, only 35% of children had leukocytosis (WBC values > 12,000/mm3), while ESR and CRP were elevated in majority of patients of all three cohorts." (PMID 34438507, 2021). "The laboratory workup usually reveals elevated erythrocyte sedimentation rate (ESR), elevated C-reactive protein (CRP), and leukocytosis." (PMID 34094774, 2021). "The laboratory profile of AOSD is a reflection of systemic inflammation, including increased erythrocyte sedimentation rate (ESR) and C-reactive protein (CRP), as well as hyperferritinemia, leukocytosis, and elevated levels of cytokines." (PMID 33785060, 2021). "Laboratory tests showed marked leukocytosis (WBC count, 33,000/μL; neutrophils, 89%) and elevated CRP (9.2 mg/dL) and serum G-CSF (214 pg/mL) levels." (PMID 34021462, 2021). "Laboratory findings vary from leukocytosis, leukopenia, lymphopenia, elevated AST, reduced albumin, elevated LDH, elevated CRP, and elevated ESR." (PMID 34786427, 2021). "Laboratory investigation in sJIA shows leukocytosis (with neutrophilia), high ESR and CRP levels, thrombocytosis, and microcytic anemia." (PMID 34682177, 2021). "Therefore, in patients with early signs of DLI and leukocytosis or elevated CRP (>1.3 mg/dL) and fibrinogen (>500 mg/dL) levels, proactive initiation of empirical antibiotic therapy may improve outcomes and prevent hospitalization even with pending exit culture." (PMID 33052592, 2021). "Due to positive RTPCR testing for covid-19, leukocytosis, the initial NLR > 3.5 and CRP = 78 mg/L, and the Lung HRCT report, the patient was quickly sent to the isolated ICU with the suspected pneumonia of Covid-19 and sepsis." (PMID 34256733, 2021).
leukocytosis (continued). "This applies, in particular, to the markers of inflammation, i.e. peripheral blood leukocytosis, ESR, CRP, or the amount of ANCA antibodies." (PMID 34445984, 2021). "Laboratory tests at admission showed marked leukocytosis (WBC count, 24,400/μL; neutrophils, 84%) and elevated CRP (13.0 mg/dL) and serum G-CSF (549 pg/mL) levels." (PMID 34021462, 2021). "The changes in parameters simply monitored in routine clinical practice include fever, C-reactive protein (CRP) increase, peripheral blood leukocytosis, lymphocytopenia, and a decrease in urine volume." (PMID 35011010, 2021). "This bacterial infection was highly associated with some urine (pyuria and urine nitrite) and hematological (high levels of CRP and ESR, and leukocytosis) factors." (PMID 33602159, 2021). "The most important cause of death in the active phase of AAV are infectious complications, and the increase in inflammatory markers (leukocytosis, ESR, CRP) is equally typical for vasculitis and severe infection." (PMID 34445984, 2021). "The most frequent laboratory findings are an increase in inflammatory indices (CRP, procalcitonin, ferritin, ERS, IL-6), cardiac markers (BNP, troponin), and D-dimer levels, leukocytosis (with lymphopenia), and reduced albumin levels." (PMID 34422717, 2021). "Laboratory tests performed at admission showed marked leukocytosis (WBC count, 34,900/μL; neutrophils, 97%) and elevated levels of CRP (8.4 mg/dL), G-CSF (452 pg/mL), and interleukin-6 (IL-6; 81.4 pg/mL)." (PMID 34021462, 2021). "Laboratory studies showed mild peripheral leukocytosis and anemia, mild transaminitis, erythrocyte sedimentation rate (ESR) 85 mm/hr., and C-reactive protein (CRP) 121 mg/L." (PMID 34020612, 2021). "Laboratory data showed leukocytosis (WBC count 14,000) with marked elevation in the neutrophil count, and high C- reactive protein (CRP) levels." (PMID 34020706, 2021). "Laboratory findings revealed leukocytosis (15,000 WBC/mm3) with neutrophilia and an elevation of C-reactive protein concentration (16.45 mg/dl)." (PMID 32426366, 2020). "Blood investigations show leukocytosis with a significantly raised erythrocyte sedimentation rate (ESR) and C-reactive protein (CRP)." (PMID 33178475, 2020). "Laboratory workup wassignificant for leukocytosis, elevated ESR, CRP, and urine drug screen positive forcannabinoids/THC." (PMID 32755249, 2020). "Investigation often reveals mild leukocytosis and elevation of inflammatory markers such as erythrocyte sedimentation rate (ESR) and C-reactive protein (CRP)." (PMID 32571258, 2020). "CBC at admission showed marked leukocytosis, thrombocytosis, anemia, and increased levels of ESR and CRP." (PMID 33167916, 2020). "Laboratoryworkup was significant for leukocytosis, elevated ESR, CRP, and urine drug screenwas positive for cannabinoids/THC." (PMID 32755249, 2020). "In 8 out of 9 patients, leukocytosis, ferritin serum levels, and inflammatory markers ESR and CRP turned to normal values within the 3-month assessment and to remain low in 6/9 patients at the 6-month visit and in 8/8 patients at the last assessment." (PMID 33122969, 2020). "Pericardial and pleura effusion as well as elevated C‐reactive protein (CRP), increased erythrocyte sedimentation rate (ESR), and leukocytosis were the most common findings." (PMID 32170340, 2020). "Blood tests revealed mild leukocytosis with lymphopenia, slight lactate dehydrogenase (LDH) elevation, normal C-reactive protein (CRP)." (PMID 33046088, 2020). "Reduced kidney function in populations at risk of CKDnt has often been shown to coincide with signs and/or symptoms of inflammation such as fever, elevated C-reactive protein (CRP), leukocytosis, or leukocyturia." (PMID 32498242, 2020). "Leukocytosis (WBC count > 15,000/uL3) was noted in 52 patients (28.1%) and a serum C-reactive protein level > 40 mg/L in 55 patients (29.7%)." (PMID 33081701, 2020).
leukocytosis (continued). "The rates of leukocytosis, erythrocyte sedimentation rate (ESR), C-reactive protein (CRP) and serum proxlotonin levels were 87%, 75%, 85.5% and 38.2%, respectively." (PMID 33072206, 2020). "Laboratory examination demonstrated leukocytosis at 12,000/μl, 87% neutrophils, and normal hemoglobin, electrolytes, creatinine, AST, amylase, and C-reactive protein." (PMID 31808013, 2019). "The initial laboratory test results showed significant leukocytosis with a white blood cell (WBC) count of 37,100/μl, elevated C-reactive protein (CRP) of 218 mg/L, and mildly elevated creatinine of 1.2 mg/dl." (PMID 31118085, 2019). "At admission blood markers of inflammation (CRP, PCT, leukocytosis) were elevated, however blood and urine cultures were negative." (PMID 31412842, 2019). "Thirteen patients (81.2%) had leukocytosis [median white blood cell count 14.800/μL (IQR = 13.000–18.700)], and 12 patients (75%) had elevated C-reactive protein [median 2.9 mg/dL (IQR = 2–12.3)]." (PMID 31554345, 2019). "During hospitalization, the patient became afebrile, but leukocytosis (15.56 × 103/uL) and inflammatory markers (ESR 120 mm/h, CRP 54 mg/L) remained elevated." (PMID 31416435, 2019). "Leukocytosis, thrombocytosis, normochromic normocytic anemia, elevated erythrocyte sedimentation rate (ESR) and C-reactive protein (CRP) values are indicative of the diagnosis." (PMID 30687221, 2018). "Non-specific laboratory findings have been reported for the diagnosis and differential diagnosis of BEO; these include leukocytosis, anemia, thrombocytopenia, elevated AST and ALT levels, and increased CRP and ESR (15-18,)." (PMID 29697933, 2018). "A laboratory examination revealed increased C-reactive protein (CRP) in 16 (88.9%) patients, an increase in the erythrocyte sedimentation rate (ESR) in 12 (66.6%) patients, and leukocytosis in six (33.3%) patients." (PMID 30558614, 2018). "Patients with a cyst infection usually present with symptoms such as flank pain and fever, mostly accompanied by an increased level of C-reactive protein (CRP) and leukocytosis." (PMID 29568734, 2018). "Patients with meningitis also required the testing C-reactive protein (CRP), leukocytosis and procalcitonin levels, as well as neurological assessments, CT scans and cerebrospinal fluid analysis." (PMID 29536253, 2018). "Laboratory studies revealed mild leukocytosis (white blood count (WBC): 13.5 × 109/L), increased levels of serum lipase > 600 U/L, amylase: 1220 U/L, and CRP: 19.6 mg/dL." (PMID 30071846, 2018). "Fever was present in 20 patients (49%), 5 patients (12%) had abdominal pain or tenderness, 8 had leukocytosis (19.5%), 37 had elevated ANC (90%) and CRP was positive in 36 cases (87.8%)." (PMID 30289914, 2018). "Typical laboratory findings include marked leukocytosis with neutrophilia, hyperferritinemia, high liver enzymes, and elevated acute-phase reactants such as erythrocyte sedimentation rate (ESR) and C-reactive protein (CRP)." (PMID 28659802, 2017). "Physical examination showed coarse crackles in lower right lung field, and patient’s laboratory workup was remarkable for elevated C-reactive protein (CRP) (16 mg/dl) and leukocytosis (16.000/mm3) with neutrophilia of 88%." (PMID 29284415, 2017). "During her hospitalization the patient manifested leukocytosis to 47,000 WBC/μL, ESR 67 mm/hr (normal range 0-42 mm/hr), CRP 17.5 mg/dL (normal range 0.02-1.20 mg/dL), and microangiopathic haemolytic anemia, with declining haemoglobin and haematocrit." (PMID 28811951, 2017). "There were significant intergroup differences in the serum levels of CRP (P = 0.012), PCT (P = 0.012) and TLC (P = 0.019), preoperative leukocytosis (P = 0.013), hypoalbuminemia (P = 0.001), and levels of PNI (P < 0.001)." (PMID 27399098, 2016). "Laboratory examination showed leukocytosis (WBC: 17300/uL), thrombocytosis (platelet: 820000/uL), an elevated CRP level (CRP: 117.4 mg/L), an elevated ESR level (ESR: 108 mm/h), and normal cardiac enzymes." (PMID 27234442, 2016).